MIR4662B (microRNA 4662b)
Synonyms: hsa-mir-4662b
Gene: MicroRNA gene on chromosome 8 (124,821,978 to 124,822,058, reverse strand). Ensembl gene ENSG00000263735.
Homologues: Orthologues: chimpanzee MIR4662B (100% identical).